Y_RNA (Y RNA )
Gene: Miscellaneous RNA gene on chromosome 4 (83,636,196 to 83,636,290, reverse strand). Ensembl gene ENSG00000201633.
Homologues: Orthologues: chimpanzee Y_RNA (82% identical), guinea pig Y_RNA (67% identical). Paralogues in human: RNY3 (85% identical), Y_RNA (85% identical), Y_RNA (84% identical), RNY3P1 (83% identical), Y_RNA (83% identical), Y_RNA (82% identical), RNY3P11 (81% identical), Y_RNA (81% identical), RNY3P14 (80% identical), Y_RNA (80% identical), Y_RNA (79% identical), RNY3P12 (78% identical), and 89 more.